CDK4 (cyclin dependent kinase 4)
Diseases named in the same sentence as CDK4 in open-access papers (continued):
Sharing a sentence is not in itself a finding about the gene and the disease.
metastatic carcinoma (10 papers, 2015 to 2024). A carcinoma which has spread from the original site of growth to another anatomic site. "Palbociclib as specific CDK4/6 inhibitor is used for the treatment of ER+ metastatic cancers." (PMID 39116089, 2024). "Furthermore, the next-generation PI3K and Cyclin-Dependent Kinase 4/6 (CDK4/6) inhibitors have been recently suggested for metastatic cancer treatment." (PMID 34207792, 2021). "More recent therapeutic options include palbociclib, a selective inhibitor of the cyclin-dependent kinases CDK4 and CDK6, approved for women with advanced metastatic cancer." (PMID 34783649, 2021). "Genes in the CMCG group (CDK4, CDK6, CDK8, GSK3B) had the most frequent copy number alterations in 86% of the primary and 65% of the metastatic cancers." (PMID 26420498, 2015). "Palbociclib, Ribociclib and Abemaciclib, as specific CDK4/6 inhibitors, obtained FDA approval for the treatment of ER-positive metastatic cancers, which combined with endocrine agents like fulvestrant and letrozole, may improve survival rates." (PMID 39116089, 2024). "In metastatic carcinoma CaOV-3, both ObR antagonists had an inhibitory effect on the cdk2/cyclin D1 complex, while in serous carcinoma, OVCAR-3, they only had an effect on cdk2 and cdk4 protein expression." (PMID 27480179, 2016).
uveal melanoma (10 papers, 2000 to 2024). A melanoma derived from melanocytes of the uveal tract. "Taken together, our preclinical study indicated that combining CDK4/6 inhibitor and cMET inhibitor would provide significant clinical benefit to patients with metastatic uveal melanoma." (PMID 33806615, 2021). "In this study, 87.5% of uveal melanoma patients’ samples were positive for phosphorylated retinoblastoma (RB), and ex vivo incubation of patients’ biopsy specimens with CDK4/6 inhibitor decreased the phosphorylation of RB." (PMID 33806615, 2021). "In human HGF knock-in NOD.Cg-Prkdc scid Il2rg tm1Wjl/SzJ mice, combination of CDK4/6 inhibitor and cMET inhibitor showed significant growth suppression in implanted metastatic uveal melanoma cells, compared to CDK4/6 inhibitor alone." (PMID 33806615, 2021). "Thus, FOXM1 contributes to the HGF-mediated protection from senescence in uveal melanoma cells treated with a CDK4/6 inhibitor." (PMID 33806615, 2021). "In uveal melanoma, another study focused on tumors resistant to MEK inhibitor (MEKi) and tolerant to CDK4/6 inhibitor (CDK4/6i)." (PMID 38214418, 2024). "This is in line with previous works demonstrating metabolic adaptation after MAPK inhibition or CDK4/6i in BRAF mutant and uveal melanoma." (PMID 37420093, 2023). "We next compared the responses and adaptation to CDK4/6 inhibition between non-transformed and uveal melanoma cells." (PMID 38030655, 2023). "The addition of the OXPHOS inhibitor, IACS-010759, to CDK4/6 plus MEK inhibitors decreased cell growth and enhanced apoptosis, suggesting that direct OXPHOS inhibition could be an approach to optimize targeted therapy treatment in uveal melanoma." (PMID 34073463, 2021).
bone metastasis (9 papers, 2020 to 2025). Transfer of a neoplasm from its primary site to bones. "Age, ECOG PS, menopausal status, visceral illness, bone metastasis, CDK4/6i type, number of metastatic locations, endocrine sensitivity or resistance status, dosage decrease, and concurrent usage of PPIs were all considered in the univariate analysis." (PMID 36984558, 2023). "We herein report a case of a 60-year-old female who presented with nausea and vomiting as the first manifestation after treated with abemaciclib (a CDK4/6 inhibitor) plus fulvestrant for 23 months due to bone metastasis of ILC." (PMID 34690920, 2021).
lung squamous cell carcinoma (9 papers, 2018 to 2024). "Abnormally expressed ASPM induces the progression of lung squamous cell carcinoma through modulating CDK4." (PMID 34987580, 2021). "In the Lung-MAP clinical trial, patients with advanced lung squamous cell carcinoma with CDK4 or CCND1/2/3 amplifications, which are molecularly similar to the p16-null state, were randomized to palbociclib or docetaxel." (PMID 30647837, 2018).
Obesity (9 papers, 2009 to 2025). Accumulation of substantial excess body fat. "As a state of chronic low-grade systemic inflammation, obesity is associated with a pro-inflammatory immune environment that is hampered by CDK4/6 inhibitors." (PMID 41388212, 2025). "In the subset of the obesity-associated tumor/cancer analysis, we identified a significant association of the CDK4 IVS4-nt40 AA genotype with BMI ≥ 30 and cancer (P = 0.002), and with BMI ≥ 30 and tumors/cancer (P = 0.007)." (PMID 19327170, 2009). "This study should prompt further work aiming at establishing the role of CDK4 in contributing to tumor/cancer genetic risk predisposition, as well as its role as a potentially effective therapeutic target gene for obesity-associated tumor/cancer management." (PMID 19327170, 2009). "The CDK4 gene lies in a chromosomal region of interest for cancer predisposition and for obesity-associated T2D genes." (PMID 19327170, 2009). "A future challenge consists in the development of novel personalized medicine to treat obesity and related diseases, repurposing some already commercialized cancer-associated therapeutic strategies such as CDK4/6 inhibitors or CDK druggable proteins that have been presented along with this review." (PMID 35681689, 2022). "From our study, we may conclude that CDK4 IVS4-nt40 AA genotype plays a role in obesity-associated tumor/cancer risk predisposition." (PMID 19327170, 2009). "Finally, in support of a metabolic function of the cyclin D/cdk4 holoenzyme in metabolism is the finding that some specific polymorphisms in the cdk4 gene could contribute to type II diabetes-associated obesity." (PMID 23355973, 2013). "Given that CDK4/6i actively modulate lipogenesis and interact with obesity-driven metabolic pathways, understanding the influence of BMI on clinical outcomes in HR+/HER2− MBC is warranted." (PMID 41514594, 2025). "Based on the interaction of CDK4/6 inhibitors on cellular metabolism, the impact of obesity on the efficacy of CDK4/6 inhibitors is under investigation." (PMID 37173991, 2023). "CDK-4 has been identified as a potential blocking target in diet-related anti-obesity treatment, as it promotes adipogenicity." (PMID 35681689, 2022). "Intracerebroventricular delivery of US Food and Drug Administration–approved (FDA-approved) cyclin-dependent kinase 4 (CDK4) inhibitor abemaciclib inhibits pRb phosphorylation in the mediobasal hypothalamus and prevents diet-induced obesity." (PMID 30185666, 2018). "Our study provides the preclinical basis for the expedient repurposing of CDK4/6 inhibitors into clinical trials for obesity management." (PMID 30185666, 2018). "We aimed at identifying a role of CDK4 IVS4-nt40 G→A gene variant in benign and/or malignant tumors and in obesity-associated benign and/or malignant tumors in an Italian adult subject dataset." (PMID 19327170, 2009). "Likewise, CDK4 and CDK6 have been implicated in metabolic disorders, including diabetes and obesity." (PMID 41388212, 2025). "Notably, a marked increase in lipogenesis and lipid accumulation was observed in the WAT of mouse models with impaired CDK6 activity, further corroborating the potential of CDK4/6 inhibition as a therapeutic strategy for obesity-related metabolic disorders." (PMID 41388212, 2025). "Recent research has further proposed these kinases as targets for obesity intervention, implying that CDK4/6i therapy may directly impact both adipose and skeletal muscle mass." (PMID 41514594, 2025). "Here, we validated this hypothesis using molecular and pharmacological approaches and, in so doing, obtained a preclinical basis for repurposing FDA-approved cyclin-dependent kinase 4/6 (CDK4/6) inhibitors for obesity management." (PMID 30185666, 2018). "This study was carried out to find out whether there is any association of CDK4 IVS4-nt40 G→A SNP with cancer and/or tumors/cancer as well as with obesity-associated cancer and/or tumors/cancer in the Italian population." (PMID 19327170, 2009).
oral cancer (9 papers, 2016 to 2025). "BEZ235, an inhibitor of PI3K/Akt/mTOR signaling and the cyclin D1/CDK-4 complex, was shown to cause synergistic radiosensitization in oral cancer cells." (PMID 40940957, 2025). "We document the molecular docking analysis data of piperine with the cell cycle proteins such as CDK2, CDK4, Cyclin D and Cyclin T for further consideration to combat oral cancer." (PMID 32831516, 2020). "After observing the inhibitory effect of AGA extracts on the viability and colony formation ability of oral cancer cells, we further evaluated by the expression levels of cell cycle regulators (CDK4, CDK6, cyclin A, B1, D1 and E2) by qPCR and Western blot." (PMID 33142749, 2020). "The expression of cyclin D1 and cyclin-dependent kinase 4 (cdk4) was reduced in the oral cancer cells, while the Cdk inhibitor – p21- was upregulated, compared to non-infected controls." (PMID 30671195, 2019). "Therefore, it is of interest to understand the molecular docking interactionsof piperine with several cell cycle proteins such as Cyclin dependent kinase 2 (CDK2), Cyclin-dependent kinase 4 (CDK4), Cyclin D and Cyclin T for further consideration in drug discoveryrelated to oral cancer." (PMID 32831516, 2020). "Furthermore, as the progression of the cell cycle is regulated by a complex of cellular cyclins and cyclin-dependent kinases (CDKs), our results suggest that the anti-proliferative effects of AGA in oral cancer cells may be through inhibiting CDK4 and CDK6." (PMID 33142749, 2020).
renal carcinoma (9 papers, 2014 to 2024). A carcinoma arising from the epithelium of the renal parenchyma or the renal pelvis. "Studies have shown that miR-21 plays a role in the transcription of cyclin D1, and by inhibiting cyclin D1 mRNA expression, miR-21 Sponge effectively controls renal cancer cell proliferation through the activation of cyclin D1/CDK4 activity." (PMID 39114567, 2024). "Collectively, our findings indicate that CDK4/6 inhibitors can increase the level of the TSC1 protein in renal cancer cells and regulate its stability." (PMID 38890443, 2024). "In summary, we not only revealed a novel RBPJ/DAPK3/UBE3A/PBRM1/p21 signaling axis but also identified a combination strategy for overcoming the resistance of renal cancer cells to CDK4/6 inhibitors." (PMID 35368029, 2022). "In summary, our results demonstrate that the RBPJ/DAPK3/UBE3A/PBRM1/p21 signaling pathway regulated the sensitivity of renal cancer cells to CDK4/6 inhibitors." (PMID 35368029, 2022). "In the present study, apart from SKCM, kidney renal papillary cell carcinoma exhibited CDK2, CDK4, KIT, and VWF Cox coefficient values of > 0, indicating that the high expression of these four key genes is a risk factor for patients with renal carcinoma." (PMID 34582363, 2021). "The cyclin D1 and related cell cycle protein RB and CDK4 were measured in cultured renal cancer cell lines." (PMID 25322986, 2014). "Therefore, this research demonstrates that miR-21 regulates the proliferation of renal cancer cells by modulating the activity of cell cycle protein D1/CDK4." (PMID 39114567, 2024). "Moreover, the RBPJ/DAPK3/UBE3A/PBRM1/p21 axis induced increased sensitivity of renal cancer cells to CDK4/6 inhibitors." (PMID 37385985, 2023). "In contrast, overexpressed PBRM1 sensitized renal cancer cells to CDK4/6 inhibitors." (PMID 35368029, 2022). "In combination with RBPJ inhibitors, CDK4/6 inhibitors synergistically enhanced renal cancer cells." (PMID 35368029, 2022). "Finally, we demonstrated that the RBPJ/DAPK3/UBE3A/PBRM1/p21 axis contributed to the sensitivity of renal cancer cells to CDK4/6 inhibitors." (PMID 35368029, 2022). "Therefore, we not only revealed a novel RBPJ/DAPK3/UBE3A/PBRM1/p21 axis but also identified a combination strategy for overcoming the resistance of renal cancer cells to CDK4/6 inhibitors." (PMID 35368029, 2022). "Moreover, our data suggest that the RBPJ/DAPK3/UBE3A/PBRM1/p21 axis modulated the sensitivity of renal cancer cells to CDK4/6 inhibitors." (PMID 35368029, 2022). "In addition, in combination with RBPJ inhibitors, CDK4/6 inhibitors showed synergistically enhanced effects on renal cancer cells." (PMID 35368029, 2022). "On the one hand, we did not combine CDK4/6 inhibitors or other drugs to further explore their therapeutic effects in animal models of renal cancer; we used the A498 and 786-O cell lines in this study, and we may have to validate the findings in more renal cancer cell lines in the future." (PMID 38890443, 2024).
renal cell carcinoma (9 papers, 2015 to 2026). "It has been shown that both PPARα pharmacological antagonism and siRNA‐mediated PPARα KD reduce the expression of c‐Myc, cyclin D1 and CDK4 in renal cell carcinoma (RCC) in vitro models." (PMID 30565681, 2019). "In prior studies CDK4/6 and PIM1 have both been shown to be potential targets in renal cell carcinoma, making abemaciclib an attractive therapeutic agent." (PMID 29221116, 2017). "Abemaciclib is a potent CDK4/6 and PIM1 kinase inhibitor, thus we evaluated the effects of abemaciclib on renal cell carcinoma." (PMID 29221116, 2017). "Additionally, CDK4/6 and PIM1 kinase appear to be viable clinical targets in renal cell carcinoma." (PMID 29221116, 2017).
rhabdoid tumor (9 papers, 2013 to 2025). An aggressive malignant embryonal neoplasm usually occurring during childhood. "Loss of SMARCB1 in rhabdoid tumors has been associated with deregulation of the cyclin D-CDK4/6-RB axis, and CDK4/6 inhibitors were among the inhibitors with the most promising activity profile in ATRT cells." (PMID 39617889, 2024). "Based on the mechanism of the preclinical efficiency of CDK4/6 inhibitor acting on SMARCA4-defective tumors, a phase I study of the CDK4/6 inhibitor Ribociclib (LEE011) was conducted in pediatric patients with rhabdoid tumors harboring SWI/SNF subunits with a high mutation rate." (PMID 36361605, 2022). "A clinical trial of the CDK4/6 inhibitor ribociclib for patients with rhabdoid tumors and other solid cancers is currently under way." (PMID 31462227, 2019). "We analyzed known deregulated pathways in rhabdoid tumors, like cdk4/6-cyclinD-RB- and MYC, using gene set enrichment analysis (GSEA)." (PMID 23764045, 2013). "While these previous studies have focused on the role of cyclin D1 in rhabdoid tumors, our analyses shed new light on the functional diversity of distinct D-type cyclins and associated CDKs in ATRT to drive cell cycle progression and possibly response to CDK4/6 blockade." (PMID 39617889, 2024).
clear cell renal cell carcinoma (8 papers, 2015 to 2023). "For instance, IGF2BP3 enhanced the proliferative activity of clear cell renal cell cancer cells by increasing the expression of cyclin-dependent kinase 4, collagen type VI alpha 1 chain, laminin subunit alpha 5, and fibronectin 1 in an m6A-dependent manner." (PMID 34621671, 2021). "In renal cell clear cell carcinoma, the miR-1 targeted and regulated cell cycle proteins such as CDK4, CDK6, Caprin1 and Slug." (PMID 26807210, 2015). "In clear cell renal cell carcinoma, IGF2BP3 suppresses cancer sensitivity to CDK4/6 inhibitor palbociclib by stabilizing CDK4 mRNA in an m6A- dependent manner." (PMID 37280679, 2023). "In clear cell renal cell carcinoma, the complex of IGF2BP3/lncRNA DMDRMR selectively interacts with their m6A-modified co-targets (including CDK4, COL6A1, LAMA5, and FN1) to promote cell proliferation." (PMID 37280679, 2023). "In clear cell renal cell carcinoma, transcription factor NFYA was reported to be able to simultaneous transactivating CCND1 and CDK4 to promote G1/S cycle transition thus accelerating tumor development and predicting poor prognosis." (PMID 35365622, 2022). "CDK4 and CDK6 expression are decreased by miR-1 and contribute to inhibition of cell cycle progression and metastasis in clear cell renal cell carcinoma." (PMID 27818681, 2016). "Collectively, these data suggest that miR-1 directly suppresses CDK4, CDK6, Caprin1 and Slug expression in clear cell renal cell carcinoma." (PMID 26036633, 2015).
fibrosarcoma (8 papers, 2007 to 2023). A malignant mesenchymal fibroblastic neoplasm affecting the soft tissue and bone. "To further explore the function of CDK6 and the differences between CDK6 and CDK4, we established two independent Cdk6-deficient MCA205 mouse fibrosarcoma cell lines (A43 and A57) using CRISPR/Cas9 technology." (PMID 37833461, 2023). "STAT1 induces cell cycle arrest in response to interferon-γ by interacting with D-type cyclins and cyclin-dependent kinase-4 in fibrosarcoma cells." (PMID 35781872, 2022). "For example, STAT1 specifically interacts with cyclin D1 and CDK4 to mediate cell cycle arrest in a human fibrosarcoma cell line after treatment with interferon (IFN)-γ." (PMID 28716119, 2017). "To further clarify the specific mechanisms responsible for the regulation of tumor growth by aberrant CDK4 expression, we established Cdk4-deficient MCA205 mouse fibrosarcoma cell line and Cdk4-deficient TC1 mouse lung epithelial cell line by CRISPR/Cas9 technology with Cdk4 specific sgRNA pairs." (PMID 37833461, 2023). "Low-grade fibrosarcoma reveals MDM2, CDK4, and SATB2 positivity." (PMID 37602060, 2023).
lymph node metastasis (8 papers, 2011 to 2025). "Among these factors, tumor thickness (p = 0.0003) and the presence of regional lymph node metastasis (p = 0.015) were significantly associated with high CDK4 expression." (PMID 34395284, 2021). "Univariate analysis of prognostic significance revealed that grade, invasive depth, vessel invasion, nerve invasion, lymph node metastasis, clinical stage, and CDK4 amplification were significantly associated with DFS and OS." (PMID 33995474, 2021). "Notably, high CDK4 expression in EMPD was significantly associated with greater tumor thickness and the presence of lymph node metastasis, which are known as prognostic factors." (PMID 34395284, 2021). "The FRQs include consideration of comprehensive cancer genome profiling (CGP) tests, ET after CDK4/6 inhibitor therapy, adjuvant therapy for small tumors without lymph node metastasis, and systemic therapy for elderly patients." (PMID 37804479, 2023).